ALCAM (activated leukocyte cell adhesion molecule)
Diseases named in the same sentence as ALCAM in open-access papers (continued):
Sharing a sentence is not in itself a finding about the gene and the disease.
tumor (continued). "Similarly, ALCAM was suggested as a BTIC marker as ALCAM was highly expressed in BTICs where it promoted neurosphere formation capacity and tumor growth while also increasing GBM invasion and metastasis to the brain." (PMID 36345944, 2022). "ALCAM is expressed in the primary tumor and also in liver metastases." (PMID 36009530, 2022). "ALCAM has previously been shown to be involved in tumor progression and metastasis." (PMID 36482887, 2022). "Shedding of ALCAM, as assessed by levels of intracellular ALCAM and extracellular domain of ALCAM in immunocytochemistry, was markedly higher in patients with colorectal cancer and is progressively increased with tumour staging." (PMID 34680335, 2021). "ALCAM is one of the few cell adhesion molecules detected in tumour-endothelial cells." (PMID 34680335, 2021). "Prospectively, a combination of inflammatory factors (such as TNF-α) and adhesion molecules (such as ICAM1 and ALCAM) neutralizing antibodies might be a useful adjuvant therapy to prevent tumor metastasis in the process of tumor treatment." (PMID 34222020, 2021). "However, the authors showed that it was the stella cells inside and around tumours are highly positive for ALCAM staining." (PMID 34680335, 2021). "This has lead to suppression of the expression of ALCAM and tumour growth in 2D and 3D cell models." (PMID 34680335, 2021). "Additionally, recurrent HNSCC was found to have significantly higher ALCAM than the primary tumours." (PMID 34680335, 2021). "Thus, there are important findings supporting the therapeutic value of using ALCAM either as a target in tumour types where ALCAM contributes to the development and metastasis." (PMID 34680335, 2021). "Interestingly, it was observed that the molecule I/F8 scFv induces ALCAM internalization and the conjugation between I/F8 scFv and the saporin immunotoxin efficiently kill ALCAM-positive tumor cells selectively." (PMID 32085563, 2020). "In cancer, ALCAM expression is a prognostic marker for various tumor types." (PMID 33270750, 2020). "ALCAM was reported to take part in tumor progression and metastasis as the target of miRNAs." (PMID 31883226, 2020). "Next, we assessed the effects of ALCAM on tumor progression and dissemination in vivo." (PMID 33270750, 2020). "Furthermore, rshCD6 inhibits proliferation and migration of tumor cell lines expressing high CD166/ALCAM surface levels (B16-F0, EL-4, and MC-205)." (PMID 33287301, 2020). "However, in one desmoplastic/nodular case, weak ALCAM staining was observed in the tumor cells of a few pale islands." (PMID 33270750, 2020). "One of these CAMs might be ALCAM, which is known to promote tumour progression by affecting diverse cellular functions including tumour cell aggregation." (PMID 31659304, 2019). "Moreover, our group recently demonstrated a role for ALCAM in the formation of both vascular networks in vivo and in tumor angiogenesis, whilst another study reported that ALCAM regulates the integrity of the blood brain barrier." (PMID 31031759, 2019). "This stratification led to interesting results regarding the prognostic impact of ALCAM expression: In tumours with high MAN1A1 expression (probably leading to high amounts of complex N-glycans), high ALCAM protein expression was significantly associated with a shorter OAS and RFS." (PMID 31659304, 2019). "Next, we aimed to clarify whether the expression level of MAN1A1 in tumours could impact the prognostic value of ALCAM and ICAM-1." (PMID 31659304, 2019). "In a follow-up experiment, we found that upregulated PAX6 expression elevated the expression of EMT marker genes (N-cadherin, vimentin, FSP-1), stem cell biomarkers (CD44, CD133, ALCAM), and the proliferation marker Ki67, yet it inhibited E-cadherin in tumor tissues as assessed by IHC." (PMID 31024010, 2019). "Additionally, ALCAM-Iso2 expression mediated an increase in metastasis and tumor cell dissemination." (PMID 29453336, 2018).
tumor (continued). "Despite this large body of evidence indicating that ALCAM is important to cancer progression, the mechanism by which ALCAM contributes to tumor progression remains unclear." (PMID 29453336, 2018). "Additional mechanistic studies support the role of ALCAM in promoting tumor progression." (PMID 29453336, 2018). "Altogether, the results suggested a different functional profile of ALCAM according to its tumor localization, i.e. whilst it correlated with epithelial markers at the superficial tumor, correlations with mesenchymal markers were observed at the invasive front." (PMID 29682175, 2018). "We further investigated the role of ALCAM at the different tumor areas." (PMID 29682175, 2018). "Among 47 tumor tissues, 95.6% of the cases showed aberrant methylation of the ALCAM gene." (PMID 29315254, 2018). "Patients with high ALCAM in tumor tissues had significantly shorter DFS." (PMID 29463803, 2018). "While at the superficial tumor, uncleaved ALCAM maintained a correlation with the major adhesion complex E-Cadherin/β-catenin; at the invasive tumor, where a more mesenchymal microenvironment takes place, it correlated with COX-2, SNAIL, MMP-9 and ETV5 mesenchymal markers." (PMID 29682175, 2018). "Furthermore, at the invasive front, we demonstrated that ALCAM-negativity was an independent prognostic marker of myometrial invasion together with the tumor grade." (PMID 29682175, 2018). "Therefore, our results also suggest that ALCAM is involved in the immunologic response to tumor cells." (PMID 29315254, 2018). "However, ALCAM expression and localization within the tumor cell have generated great controversy, and its relation to prognosis remain still unclear." (PMID 29682175, 2018). "Whereas at the superficial area of the tumor ALCAM correlated with the E-Cadherin/β-Catenin adhesion complex, at the invasive front ALCAM could be shed by MMP-9 in poor prognosis scenarios." (PMID 29682175, 2018). "Disruption of ALCAM–ALCAM interactions between cells promotes tumor cell motility and metastasis, then shedding may predict tumor progression at a molecular level." (PMID 29682175, 2018). "In fact, the potential of ALCAM-negativity as an independent prognostic factor of myometrial invasion was confirmed by multivariate logistic regression analysis with an OR 3.273, together with the tumor grade (OR 3.484)." (PMID 29682175, 2018). "In addition, GBM cells overexpressing a soluble isoform of ALCAM increased tumor cell invasion in vitro and were more tumorigenic in vivo." (PMID 29872504, 2018). "Also, the level of inflammatory markers including TNFα, NF-κB p50 subunit and IL-4 in tumor tissues showed positive correlation with the level of ALCAM transcripts." (PMID 29315254, 2018). "Since ALCAM mRNA levels remain unaltered during tumor progression in four independent patient cohorts and fail to predict overall survival by univariable and multivariable analyses, we conclude that ALCAM gene expression is not a viable biomarker for BCa prognosis." (PMID 27894096, 2017). "Further statistical interrogation provides evidence that urinary ALCAM is a significant independent predictor of overall survival after adjusting for age, tumor stage, positive lymph-node status, and urinary hemoglobin and improves accuracy of prediction (i.e. discrimination) by 3.3%." (PMID 27894096, 2017). "To determine if protein expression of ALCAM in BCa correlates with tumor stage and/or patient outcome, we performed immunofluorescence staining on tissue microarrays (TMAs) constructed of high-grade BCa specimens collected during cystectomy as described in the methods." (PMID 27894096, 2017). "ALCAM forms adhesive interactions between neighboring epithelial cells but cohesion is disrupted by membrane proximal, proteolytic cleavage and release of the ALCAM ectodomain from mobile tumor cells." (PMID 27894096, 2017).
tumor (continued). "In addition, expression level of ALCAM was negatively correlated with microvascular invasion and tumor size recognized as prognostic factors." (PMID 29375378, 2017). "Activated Leukocyte Cell Adhesion Molecule (ALCAM) is a cell surface protein capable of homotypic cell-cell adhesion, the disruption of which, contributes to both normal cell migration and the metastatic dissemination of tumor cells." (PMID 27894096, 2017). "Therefore, the baseline model (Model 1) that was used to assess the benefit of adding urine ALCAM to predict 3-year OS included age, tumor stage, positive lymph-node status, and urine hemoglobin." (PMID 27894096, 2017). "The adhesion molecules evaluated in this study, namely ICAM-1, VCAM-1 and ALCAM, are known to be involved in tumor cell attachment to the vascular endothelium and are directly implicated in the progression of tumor growth, including early stages of metastasis seeding in the brain." (PMID 26706037, 2016). "Also, prognostic significance of ALCAM expression in primary tumor cells and metastatic lesion cells was evaluated in the context of 5-year observation." (PMID 26134500, 2015). "In this study, we found that most AA tumors had low or complete loss of ALCAM expression at intercellular junctions regardless of the basal-like status, level of differentiation, tumor size, lymph node involvement and age." (PMID 25255861, 2014). "We examined membranous ALCAM in the context of patient characteristics and tumor pathology." (PMID 25255861, 2014). "After cleavage from the tumor cell surface, s-ALCAM can be detected in the blood serum." (PMID 22745698, 2012). "ALCAM-induced N-cadherin junction formation might enhance the ability of tumor cells to move into different surroundings." (PMID 22745734, 2012). "Though there was a high frequency of ALCAM expression in our cell line collection, there is always a concern that it may be due to a selection process inherent in creating tumor-derived cell lines." (PMID 23024593, 2012). "By evaluating ALCAM reactivity in tumor cells we were able to show that ALCAM expression is present in a substantial portion of tumors but does not correlate with prognostic markers like clinical stage, grading, age or histological type, or with patients' survival." (PMID 22475274, 2012). "Here we were able to show that ALCAM expression in tumor cells might be a predictive marker for response to chemoradiation in this cancer entity." (PMID 22475274, 2012). "Therefore ALCAM at the cell surface plays a divergent role in the progression of different tumor types." (PMID 21364949, 2011). "In addition, ALCAM is a marker of cancer stem cells and its expression at the tumor cell surface has been correlated with shortened survival in colon-rectal cancers and with the vertical growth phase of progression in cutaneous melanoma." (PMID 21364949, 2011). "The level of ALCAM expression is variable in different tumor types." (PMID 20929568, 2010). "Anti-ALCAM antibodies reduced the number of intravascular tumor cell clusters." (PMID 20929568, 2010). "Recently, an internalizing human anti ALCAM-scFv was also selected by phage display on whole tumor cells and then conjugated to seed saporin in a similar way, showing specific killing activity against target tumor breast cells." (PMID 22069572, 2010). "The ALCAM promoter is extensively methylated in tumor cells that lack ALCAM expression." (PMID 20929568, 2010). "These highly-expressing ALCAM tumor cells formed several clusters while perfusing the pulmonary vasculature of the rat lung, two function blocking ALCAM antibodies consistently reduced significantly the total number retained in the rat lung, while IgG had no impact." (PMID 20929568, 2010).
tumor (continued). "In the same line, progression-free survival was significantly shorter in tumours displaying high levels of ALCAM in comparison with medium- and low-expressing tumours (median progression-free survival times of 7, 8 and 17 months for high, medium and low expression, respectively, P=0.008)." (PMID 19603023, 2009). "In this analysis, increased ALCAM intensity expression proved to be an independent prognostic marker for OS (P=0.0001) in addition to adjuvant treatment of chemotherapy (P=0.0001) and tumour stage (P=0.007)." (PMID 19603023, 2009). "In addition, increased as well as reduced expression of ALCAM has been correlated with poor prognosis, depending on the tumour type." (PMID 19603023, 2009). "In addition, knocking ALCAM from MET5A mesothelial cells resulted in a marginal reduction of adhesion by control cancer cells that express high levels of ALCAM, consistent with the argument that ALCAM in mesothelial cells has a role of the soil receptor for the tumour seeding ALCAM." (PMID 36614319, 2023). "Thus, there has been a great interest in investigating ALCAM in these tumours." (PMID 34680335, 2021). "However, this connection of negative ALCAM and nodal involvement is greatly enhanced, by a factor of 8, when the tumours also had KRAS mutation." (PMID 34680335, 2021). "Taken together, this suggests ALCAM may act as a mediator of tumor cell interactions with the surrounding micro-environment and a regulator of signal propagation within the cell, though this appears to be dependent on the particular environment or factors present." (PMID 31695844, 2019). "Also, ALCAM expression in tumor cells can be downregulated by DNA methylation." (PMID 29315254, 2018). "However, studies of ALCAM in ascites fluid from patients with ovarian carcinomatosis suggest ALCAM in tumor-adjacent fluids, other than blood, could predict outcome." (PMID 27894096, 2017). "Therefore, we hypothesized that elevated levels of urinary ALCAM would be indicative of invasive tumor progression and, thus, serve as a prognostic biomarker in BCa." (PMID 27894096, 2017). "ALCAM, another member of the IgSF, may also induce apoptotic resistance in tumour cells." (PMID 22272201, 2012). "Our tracking of MSC marker expression revealed progressive CD34 upregulation alongside declining ALCAM, CD44, and ICAM1 levels, indicating complex transcriptional reprogramming during MSC-to-tumor cell transitions." (PMID 40959090, 2025). "Nevertheless, NCAM1, NRCAM, SLIT2, ALCAM, NRP1, and NRP2 also showed mild expression in Stage 4 tumor cells (primarily in cluster cIV)." (PMID 40448172, 2025). "In early‐stage BM from NSCLC, tumor cells adhere to endothelial cells via VLA‐4/VCAM‐1, ALCAM/ALCAM, and LFA‐1/ICAM‐1 interactions." (PMID 40719284, 2025). "We revealed that hypoxia is associated with the activated leukocyte cell adhesion molecule (ALCAM)high macrophages enrichment and CD8+ T cell exhaustion around the tumor boundary in the tumor spatial microenvironment." (PMID 38956900, 2024). "There was a concentration dependent inhibition of tumour cell adhesion on mesothelial cells and at higher concentration, the AZM475271 achieved the same degree of inhibition as the soluble ALCAM antagonist." (PMID 36614319, 2023). "Regarding tumorigenesis, they included interference of homotypic CD166/ALCAM-CD166/ALCAM interactions needed for optimal proliferation and migration of mouse tumour cells (right-hand side)." (PMID 38139340, 2023). "Tumor cell-macrophage hybrids express both macrophage (CD14, CD68, CD163, CD204, and CD206) and tumor-specific markers (ALCAM, MLANA, KRT, EpCAM, CXCR4, and CD44)." (PMID 35242760, 2022). "Increased expression of ALCAM in PDAC is an independent prognostic marker for poor survival and early tumor relapse." (PMID 36009530, 2022). "ALCAM, E-selectin, ICAM/LFA-1, and VCAM-1/VLA-4 have all been shown to play a part in the tumour cell invasion into the brain parenchyma." (PMID 34504791, 2021).
tumor (continued). "The bio-distribution assay confirmed that the LS174 tumor uptake was 1.4 ± 0.15%ID/g (ALCAM-3Lamide-DOTA-cDb) and 2.6 ± 0.53%ID/g (ALCAM-3 L-thioether-DOTA-cDb)." (PMID 32096011, 2020). "The CD6 ligand CD166/ALCAM is involved in the maintenance of tissue architecture, immune responses and tumor progression." (PMID 33287301, 2020). "There is growing evidence that CTC population is extremely heterogeneous, with a small percentage of tumor cells, called cancer stem cells (CSCs) expressing CD44, ALCAM, POU5F1B, able to proliferate and form new tumors." (PMID 31552188, 2019). "We finally confirmed that in an invasive scenario, ALCAM and MMP-9 are important actors at the invasive front of the tumor." (PMID 29682175, 2018). "ALCAM maintained a close and inverse relation with MMP-9 at the invasive front of the tumor (p=0.004; OR 0.26)." (PMID 29682175, 2018). "We injected sorted ALCAM+ GCTB28 cells with different gradient into the tibial marrow cavity of nude mice and monitored tumor formation in different time point after inoculation." (PMID 29463803, 2018). "Our study found that ALCAM+ subpopulation sorted from GCTB28 cells proliferated faster than the ALCAM− cells and more fully recapitulated tumor heterogeneity." (PMID 29463803, 2018). "Next, we analyzed the relationship between ALCAM expression and clinical features of CRC like tumor stage, nodal status, distant metastasis, tumor grade, age and gender." (PMID 28537909, 2017). "We found that miR-483-5p promotes tumor invasion in HCC, andactivated leukocyte cell adhesion molecule (ALCAM) is characterized as a direct and functional target of miR-483-5p in HCC cells." (PMID 29375378, 2017). "The effects of selenoglycoproteins and tumor cell infusion on the expression of selected cell adhesion molecules, namely ICAM-1, VCAM-1, and ALCAM, were evaluated by quantitative reverse transcription PCR." (PMID 26706037, 2016). "Thus, it is believed that the membranous expression of ALCAM reflects the maintenance of intercellular stability and that the cytoplasmic location, resulting from rearrangement of the intercellular junctions, characterizes tumor cells with high potential for invasion and metastasis." (PMID 26339605, 2015). "Down-regulation of ALCAM is more severe in AA women than in CAU women even when the tumors have identical characteristics, such as histological grade, tumor size and lymph involvement." (PMID 25255861, 2014). "The expression of ALCAM, CN130, DAXX, GAL1, PHF6 and XPA were significantly correlated with tumor grade and stage." (PMID 23819605, 2013). "Variation in sALCAM among studies may have multiple causes: sALCAM must pass through the barrier of tumor tissue and vascular endothelial cells to be flushed into the blood stream, and sequential sectioning has failed to establish a direct relationship between ADAM17/TACE and ALCAM." (PMID 23940674, 2013). "By this approach we could demonstrate that histopathological and clinical tumor characteristics were similarly distributed between all groups, indicating that the predictive effect of ALCAM expression was independent and not due to associations with known prognostic parameters in subgroups." (PMID 22475274, 2012). "In contrast to E-cadherin, another type of adhesion molecule, the immunoglobulin superfamily (including NCAM, MCAM, ALCAM and L1CAM, among others), is often highly expressed in metastatic tumour tissues." (PMID 22610942, 2012). "They concluded that ALCAM would be a very robust, but inert cell-surface marker for NSCLC tumor-initiating-cells." (PMID 22745698, 2012). "Patients whose tumours showed ER/HER2 negativity, and high OPN and low ALCAM expression (group 2) turned out to be the group having the highest risk for shorter DFS and OAS compared with all the other groups regardless of the administered therapy." (PMID 20736952, 2010).